STAT3 (signal transducer and activator of transcription 3)
Diseases named in the same sentence as STAT3 in open-access papers (continued):
Sharing a sentence is not in itself a finding about the gene and the disease.
tumor (continued). "We found that STAT3-KD in both GBMX16 and GBMX10 GICs markedly reduced tumor formation as compared to control GICs not treated with Dox." (PMID 29774125, 2018). "mTORC1 inhibition by rapamycin sensitized the tumor to crizotinib: Simultaneous treatment inhibited the activity of ALK and consequently its targets STAT3 and AKT, while crizotinib as single agent did not." (PMID 29755689, 2018). "STAT3 overexpression in HT cells encouraged DLBCL cell dissemination and increased the number of CTCs without significantly affecting primary tumor growth." (PMID 30209389, 2018). "They showed that HDAC3 is aberrantly co-expressed with pSTAT3 Tyr705 in DLBCL tumor samples but not in normal blood B-cells and that HDAC3 complexed with STAT3 in pSTAT3 Tyr705-positive DLBCL cell lines (i.e., Ly3 and DHL2)." (PMID 29914167, 2018). "Other upregulated genes such as PTEN, ZEB2, STAT3 and IL1B did not align with tumour expression pattern as they are consistently downregulated in the patients datasets." (PMID 30176945, 2018). "siRNA knockdown of STAT1 but not STAT3 reduced IFN-g- and IL-27-induced PD-L1 protein expression on tumor lines and Monos." (PMID 30400822, 2018). "When compared with negative controls, RBE cells overexpressing STAT3 showed increased proliferation ability in vitro and in vivo, as estimated by CCK8 and subcutaneous tumor-burdened assays, respectively." (PMID 28032598, 2017). "In a tumor xenograft model bearing HSC3 cell tumors, NC suppressed tumor growth and induced apoptosis by regulating STAT3 signaling without liver or kidney toxicity." (PMID 29207645, 2017). "The central role of S1PR1 in Stat3 signaling has been established in tumor and immune cell growth but its importance in CNTF/Stat3-induced growth mechanisms has not been addressed in injured adult neurons." (PMID 29234527, 2017). "In this study, we have found an association between the expression of the follow proteins (STAT5, STAT3_pS727, BMP6, CD74, TFRC, INHA, and STAT5_pY694) involved in iron homeostasis and the type of tumor tissue (breast cancerous vs. non-cancerous)." (PMID 28216608, 2017). "For activation of STAT3 both EGFR mediated signaling as well as IL-6 signaling has been shown to be relevant and in NSCLC tumor cells JAK1 and not JAK2 was determined as the signal relaying kinase." (PMID 28402937, 2017). "For example, although IL-27 can simultaneously activate STAT1 and STAT3, the activation of STAT1 rather than that of STAT3 mediates the tumor suppressor role of IL-27." (PMID 28626343, 2017). "STAT3, STAT5, and STAT6 exhibit tumor-promoting functions, not only in cancer cells and cancer stem cells, but also in other cellular constituents of the tumor microenvironment, such as stromal cells and immune cells." (PMID 28903353, 2017). "PFE treatment resulted in inhibition of UVB-induced phosphorylation of STAT3, and NFκB/p65 with a concomitant decrease in the protein expressions of iNOS, and COX-2 in uninvolved skin from tumor-bearing mice and skin tumors compared to non-PFE-treated animals." (PMID 28125044, 2017). "Tumor samples derived from NSCLC patients can show robust activation of AKT, ERK, and STAT3 while EGFR is not activated." (PMID 29177004, 2017). "These pathways were not enriched in the HepG2 tumor sample, although four were increased in the HepG2 cell sample (TNFα signaling via NFκB, allograft rejection, IL-6/JAK/STAT3 signaling, inflammatory response)." (PMID 29259231, 2017). "We previously demonstrated that exogenous IL11 phosphorylates STAT3, but not ERK, or AKT in Ishikawa, HEC1A and AN3CA cells in vitro and Ishikawa and HEC1A xenograft tumours in vivo, confirming that IL11 likely does not act via these pathways in these cells." (PMID 28186993, 2017). "However, gemcitabine could not prevent STAT3 phosphorylation in IL-6-treated tumor cell lines." (PMID 27687804, 2016).
tumor (continued). "Of note, poorly or nondifferentiated tumor tissues showed higher levels of EBI3, IL-12p35, gp130, and p-STAT3 expressions than well or moderately differentiated tumor tissues." (PMID 27247488, 2016). "To clarify the regulation by Anxa 2 and STAT3 on tumor growth of CRC, we examined the proliferation of Caco-2 cells, in which Anxa 2 was upregulated or was knocked down, in which STAT3 was knocked down or not." (PMID 27274723, 2016). "When correlated with tumor growth of Myc Stat3 CKO mice, those tumors lacking Stat 3 excision had more rapid tumor growth relative to tumors with Stat3 excision." (PMID 27589562, 2016). "In the present study, preoperative serum CA125 level and mucin-16 expression in primary tumor tissues correlated with the nuclear levels of JAK2 protein, rather than its downstream effectors STAT3 or pSTAT3 (data not shown)." (PMID 27081079, 2016). "In both models STAT3, but not STAT5, was activated in vitro and in vivo, in primary tumours and bone metastasis." (PMID 27406745, 2016). "IDO expression can be blocked by inhibitors of c-KIT or mTOR (downstream of the c-KIT/PI3K/AKT pathway), with resultant enhancement of anti-tumor T cell responses, but the potential role of PI3K/AKT/CREB signaling or STAT3 activation has not been addressed." (PMID 26343197, 2015). "Serum IL-6, through p-STAT3 rather than p-STAT1 signal pathway, affected hepatic function, tumor progression, and determine HCC patient survival." (PMID 25908103, 2015). "Therefore, caffeine or another non-toxic inhibitor of the STAT3 pathway could constitute an efficient approach to normalize active breast stromal fibroblasts and hence participates in efficient eradication of tumor cells through targeting their supportive milieu." (PMID 24595168, 2014). "Based on these data, it is not surprising that vaccination with exogenous, STAT3-depleted DC was shown to enhance anti-tumor CD8+ T cell responses and improve control of tumor outgrowth." (PMID 23874338, 2013). "When the tumor subtypes without a counterpart were analyzed via GSAA, we observed PDGFRB_STP co-expressed with aberrantly expressed MYC and STAT3 only in luminal A." (PMID 23516564, 2013). "Statistics showed STAT3 correlated significantly to both WHO classification (χ2 = 13.742, P < 0.05) and Masaoka staging (χ2 = 8.623, P < 0.05), but not to age, gender and tumor mass." (PMID 23590999, 2013). "STAT3 is constitutively activated in human HCC tissues, but not in adjacent non-tumor liver parenchyma or normal liver tissue." (PMID 22470194, 2012). "These were sufficient to design a new discriminating hpdODN that inhibits STAT3 and not STAT1, thereby inducing tumor cell death without interfering with STAT1-dependent processes." (PMID 22423663, 2012). "Pharmacological inhibition of P-STAT3 by S3i-201 for 24 hours resulted in reduced tumour proliferation at a concentration of 100 μmol/L in ESFT cell lines, but not in the STAT3-negative PC3 cell line." (PMID 22315522, 2012). "The percentage of vessel and muscle invasion by STAT3-silenced tumors was 22.22% (2/9) and 33.33% (3/9) compared to 60% (6/10), 80% (7/10) and 70% (7/10), 80% (8/10) in SW1990 tumor and negative control tumor, respectively." (PMID 21991388, 2011). "Some authors have reported that p-STAT3 is present in high levels in GBM cell lines and in greater than 75% of tumor tissue samples; however, other authors have failed to corroborate these findings." (PMID 22190972, 2011). "The staining intensity in tumours treated with WP1066 was much stronger than that in control tumours, which was the inverse of what was observed with p-STAT3 immunostaining (data not shown)." (PMID 20461084, 2010). "Similar total STAT3 immunostaining was observed in both vehicle-treated and WP1066-treated tumours, suggesting that WP1066 inhibited phosphorylation of STAT3 without modulating STAT3 expression (middle row)." (PMID 20461084, 2010).
tumor (continued). "Taken together, we show high constitutive STAT3 phosphorylation in primary tumour samples from patients with SCLC but not from NSCLC, and constitutive and CXCL12-dependent activation of the JAK2/STAT3 pathway in SCLC cell lines." (PMID 19455144, 2009). "We observed an increase in STAT3, but not STAT1 (not shown), activity in tumor cells-monocyte co-cultures, as compared to each cell type cultured individually." (PMID 19718269, 2009). "Our observations of comparable levels of pSTAT3 between healthy and tumor tissues and a lack of correlation with MVD or mature DC infiltration do not support the implementation of STAT3 inhibitors as anti-angiogenic or immunostimulatory therapeutics in NSCLC." (PMID 19519895, 2009). "Perhaps it is the tumor expression of IL-23, IL-6, epidermal growth factor or Janus kinase 2 or an undefined factor that ultimately regulates the expression of PBMC p-STAT-3 levels, but this was not determined in our current study." (PMID 19900287, 2009). "Several genes thought to play a role in the processes of invasion, tumour progression and metastasis (MME, STAT3, DCBLD2, S100A10, CD9, S100A8) were highly downregulated in the NE vs the non-NE tumour group." (PMID 18827820, 2008). "A key future direction is to explore if EGF/STAT3 signaling can ectopically induce SOX11 in non-tumorigenic cells, and if so, whether this prompts TWIST expression and a tumor-like phenotype." (PMID 41511366, 2026). "STAT3 acts as a "double-edged sword": hyperactive STAT3 drives metastasis and BRAF inhibitor resistance in advanced carcinomas, yet paradoxically acts as a tumor suppressor by restraining the Warburg effect via non-canonical mitochondrial localization." (PMID 42193894, 2026). "Since the target genes of the oncogenic transcription factor, STAT3, were upregulated in tumor and nontumor tissues from DKO-HFHSD mice, we speculated that in HFHSD-fed DKO mice, STAT3 was activated before hepatocarcinogenesis." (PMID 39670881, 2025). "Second, given that STAT3 signaling is not exclusive to tumor cells, the STRESS signature may reflect contributions from multiple cell types in the tumor microenvironment." (PMID 40701148, 2025). "By targeting STAT3, BBI608 may not only sensitize cells to MDM2 inhibition but also potentially modulate the tumor microenvironment, although this was not directly assessed in our in vitro model." (PMID 40943567, 2025). "Translation of these results to a pharmacological scenario has illustrated that combining daraxonrasib with afatinib, an irreversible EGFR/HER2 tyrosine kinase inhibitor, and SD36, a selective STAT3 PROTAC, also led to robust tumor regression without evidence of tumor resistance." (PMID 41159877, 2025). "Moreover, in isolated tumor cells, the N-terminally truncated STAT1 and, to a much lesser extent STAT3, were hyperphosphorylated irrespective of cytokine stimulation, as compared to non-transformed spleen cells from their WT-expressing littermates." (PMID 40287766, 2025). "This suggests that the increased requirement for STAT3 signaling in tumor cells of KPT tumors, including the possible involvement of tumor cells that hitherto did not respond to IL-11, appears to be realized by the coordinated upregulation of IL-6 and its cognate IL-6Ra receptor subunit." (PMID 39128004, 2024). "However, in the presence or absence of STAT3 knockdown, no significant change was observed in PCK2 mRNA level between TRCs and bulk tumor cells, indicating that STAT3 did not regulate PCK2 through transcriptional level." (PMID 38720107, 2024). "Moreover, a lack of miR-21 reduces STAT3 and Bcl-2 activation, leading to increased apoptosis in CAC mouse tumor cells." (PMID 38542332, 2024). "In addition, the chemical inhibitors targeting STAT3 and HIF-1α were dissolved in dimethyl sulfoxide, which is toxic and not suitable for use in the tumor xenograft model." (PMID 36814597, 2023).
tumor (continued). "Our lab showed that the loss of Adenomatous Polyposis Coli (APC) caused an intrinsic resistance to doxorubicin (DOX), potentially through an enhanced tumor-initiating cell (TIC) population and the increased activation of STAT3 mediating the expression of MDR1 in the absence of WNT being activated." (PMID 37108784, 2023). "Thus, not only STAT3 but also p65, which is considered a prime inducer of tumor inflammation with its most deleterious effects, can protect against CSC enrichment upon TME Stimulation, when the guardian roles of STAT3 are absent." (PMID 37190183, 2023). "Specifically, non-protein-coding transcripts regulate STAT3 signaling in HCC, and their inhibition by antitumor agents may affect tumor progression." (PMID 37085753, 2023). "STAT3-knocked-down ADOCC failed to form metastases and resulted in slower tumour growth." (PMID 36429126, 2022). "Consequently, JAK–STAT activation, in a JAK1/JAK2- and STAT1/STAT3-dependent manner, is required for the transition to a stem-like, multilineage and EMT state but not for the tumor cells that have completely redifferentiated to an NE-like lineage." (PMID 36065066, 2022). "Fractions with the highest concentration of proanthocyanidin (PAC) inhibited cellular viability and reduced tumor volumes while also reducing p-JAK1, p-JAK2, p-JAK3, p-STAT1, p-STAT3, and p-STAT5 (although there was no change in total STATs, total JAKs were decreased)." (PMID 36355554, 2022). "However, EZH2 knockdown with or without PRADX overexpression in tumor cells revealed increased levels of BLCAP and reduced nuclear levels of p-STAT3." (PMID 35574370, 2022). "Previous in vivo and in vitro studies using head and neck cancer cells found that combined treatment of cisplatin and curcumin inhibited tumor angiogenesis by 62%, VEGF production by 83%, STAT3 phosphorylation by 94%, and CAL27-CisR tumor growth by 77% compared to the non-treated group." (PMID 35163459, 2022). "Although STAT3 and YAP have been reported to promote EMT, invasion and proliferation in various cancers, previous studies investigating STAT3 in SCLC have mainly focused on drug resistance and not EMT, invasion or tumor progression." (PMID 35885009, 2022). "In conclusion, we show that in the absence of STAT3, IL-6 induced prolonged STAT1 signaling and expression of STAT1 target genes, which suggests an interplay of STAT1 and STAT3 signaling in the presence of proinflammatory IL-6 in the tumor microenvironment." (PMID 35267462, 2022). "Consequently, in a mouse model, the absence of OB-R resulted in reduced tumor growth and invasiveness by reducing JAK/STAT3 and ERK1/2 signaling." (PMID 35625629, 2022). "The regulation of PD-L1 expression differs significantly between different cancer types, as well as between tumor cells and non-tumor cells due to variation of aberrations of activation of many signaling pathways such as RAS/RAF/ERK, PI3K/AKT, and JAK/STAT3, among others." (PMID 35625917, 2022). "DFT2 cells express comparable levels of STAT3 to DFT1, which do not change upon treatment with IFNγ in either cell line, and lower levels of Interleukin 1 Receptor, Type 1 (IL1R1), which is upregulated by both tumours in response to IFNγ." (PMID 34780568, 2021). "We do not propose STAT3 or JAK1/2 inhibition as promising therapies to be combined with opioids, as this could result in severe immunosuppression or altered stromal-tumor cell signaling." (PMID 33465556, 2021). "By restraining the JAK/STAT3/c-MYC pathway, metformin could inhibit the transition of normal endothelial cells toward tumor endothelial cells induced by tumor conditioned medium." (PMID 33903283, 2021).
tumor (continued). "Although no small-molecule inhibitors of STAT3 have yet been approved to treat cancer, some early-phase clinical trials with compounds that inhibit STAT3 activity (AZD9150 or napabucasin) show anti-tumour effects in patients with advanced carcinoma." (PMID 34407787, 2021). "However, in contrast to human studies, STAT1, but not STAT3 or STAT6, was responsible for immunosuppressive activity of TAMs derived from colon CT-26 tumor-bearing BALB/c mice." (PMID 32486098, 2020). "However, despite both STAT3 and CD44 acting as pivotal regulators of tumor angiogenesis, there is currently no direct evidence of functional crosstalk between STAT3 and CD44 during angiogenesis promotion." (PMID 33335857, 2020). "We also assessed the effect of RBP4 overexpression on STAT3 phosphorylation in 67NR/RBP4 cells in vitro (as well as in 67NR/RBP4 and 4T1/RBP4 tumor cell lysates), and we did not observed significant differences between wild-type or empty vector-transduced cell lines and Rbp4-transduced cells." (PMID 32156052, 2020). "Furthermore, through microscopic imaging, we uncovered tumor vessels in ABC samples but not GBC samples to be coated by FVIII- and STAT3-positive endothelial cells." (PMID 32664527, 2020). "In order to analyse in which cardiac cells tumour disease induces STAT3 activation, we performed immunofluorescence analyses of STAT3 (Tyr705) phosphorylation combined with wheat-germ agglutinin (WGA) in WT and CKO mice with and without B16F10 tumours." (PMID 31667271, 2019). "While tumour disease did alter total STAT3 protein levels in WT mice, the ratio of phosphorylated STAT3 to total STAT3 was higher in tumour diseased CKO mice, suggesting that non-cardiomyocytes display a higher STAT3 activation state compared with WT B16F10-TM." (PMID 31667271, 2019). "Second, as STAT3 is the key switch effecting PMT, its early implementation when the tumor is STAT3-high and non-mesenchymal could possibly mitigate its subtype switching." (PMID 31399589, 2019). "Overexpression of PTPN13 in HCC cell lines MHCC97H and HepG2 significantly reduced phosphorylation of ERK1/2 and STAT3 but not Src, indicating that PTPN13 may act as a tumor suppressor via ERK1/2 and/or STAT3 signaling in HCC." (PMID 29558404, 2018). "Negative correlation of STAT3 and PTPN6 in PTCL tumor samples was also analyzed by IHC (n = 146)." (PMID 30420593, 2018). "To determine whether the CT inhibited the expression of STAT3, SIRT3, HIF‐1α, GLUT1, LDHA, and HK2 in vivo, we performed qRT‐PCR to detect these genes expression in tumor tissues from the mouse with or without the treatment of CT." (PMID 30094960, 2018). "However, STAT3-KO MT330 cells failed to form intracranial tumors in vivo, probably through STAT3 affecting the tumor microenvironment." (PMID 29774125, 2018). "However, the discontinuation of paclitaxel and momelotinib treatment no longer suppressed JAK2/STAT3 activation and CSC-like development, thus allowing the resumption of tumor growth and dissemination." (PMID 29682172, 2018). "Notably, the activation of STAT3 has strong negative feedback from SHP phosphatases and suppressor of cytokine signaling 3 (SOCS3), which is inhibited in tumor cells." (PMID 30104473, 2018). "Staining of tumor tissue with Ki67, a marker for proliferating cells, revealed high numbers of proliferating cells in GBMX16 control and STAT3-rescued tumors as compared to the near absence of Ki67-positive cells in STAT3-KD tumors." (PMID 29774125, 2018). "Therefore, we concluded that the expression of p-STAT3 was significantly correlated with tumor metastasis, TNM stage, and poor prognosis but not with age, gender, tumor size, or differentiation grade." (PMID 29333928, 2017).